NOTCH1 (notch receptor 1)
Diseases named in the same sentence as NOTCH1 in open-access papers (continued):
Sharing a sentence is not in itself a finding about the gene and the disease.
tumor (continued). "However, overall, it is apparent that hypoxic gliomaspheres mimic the in-vivo tumor condition better than the other tissue culture model as the upregulation of Notch genes (Notch1, Notch2, Notch3, Dll1, Hes1, Hey1 and Hey2) is further enhanced upon exposure to hypoxia." (PMID 25734817, 2015). "However, combining GSI-I and BTZ was associated with total lack of expression of Notch1 in the corresponding tumor tissues." (PMID 25879451, 2015). "Particularly, this investigation tested the hypothesis that inactivated Notch1 may play a suppressive role in tumor progression through defining Notch1 or N1-ICD-V1754 status in relation to clinicopathological factors such as tumor differentiation, nodal status and clinical stage." (PMID 25653136, 2015). "In addition, the expression levels of Notch1 and Jagged1 were found to markedly correlate with tumor size, grade and TNM stage, as well as disease relapse, suggesting that the Notch pathway may be associated with the oncogenesis process of RCC." (PMID 24959218, 2014). "Furthermore, the effect of activated Notch1 signaling (NICD) on the regulation of p21 expression may differ in various tumor cell types." (PMID 24396472, 2014). "Our results also suggest that multinucleated giant cells are not osteoclasts, but angiogenic tumor cells in which ADAM10/Notch1 signaling is activated and might be implicated in tumor cell migration." (PMID 24548763, 2014). "NOTCH1 signaling is likely to be a key player in organoid PGL tumorigenesis and could be implicated in the resistance to radiotherapy and anti-angiogenic agents shown by this tumor type." (PMID 23955600, 2013). "Therefore, Notch1 expression in tumors may function as a double-edged sword, most probably depending on the whole complex a given tumor faces." (PMID 23409141, 2013). "We found that Notch1 was expressed in the basal layers of normal esophagus epithelia while in tumors, if it was positive, rather homogeneously expression was seen, except in the well differentiated tumors where mainly basal layers of the tumor nests were positive." (PMID 23409141, 2013). "Moreover, given that Notch1 appears to be the primary Notch receptor responsible for developmental angiogenesis, together with the results obtained using specific anti-Notch1 antibodies in tumors, Notch1 seems to be the predominant mediator of Notch signaling in tumor angiogenesis." (PMID 23601498, 2013). "If that is true there might be clinical significance of Notch1 expression in tumor samples." (PMID 23409141, 2013). "For example, in neuroendocrine cells, Notch1 may act as a tumor suppressor." (PMID 23671619, 2013). "Finally, a role for NOTCH1 in maintenance of cancer stem cells has been proposed in some tumors; if such cells are rare, assessment of NICD1 in bulk tumor cell populations may underestimate the contribution of NOTCH1 to the malignant phenotype." (PMID 23825651, 2013). "Conversely, Notch1 may act as a tumor suppressor in mouse skin." (PMID 24312514, 2013). "However, quantitative real time PCR analysis revealed that NGP tumor cells also express Notch1." (PMID 24066611, 2013). "Interestingly, Notch-1 and Dll1 were specifically up-regulated in residual tumors compared to untreated primary tumors, disseminated cells, or metastases, suggesting a unique role for these genes in residual tumor biology." (PMID 23520493, 2013). "However, since Notch1 and JAG1 are up-regulated in SS, the possibility that the down-regulation of PTEN observed in these tumor may be, at least in part, related to Notch1 signaling de-regulation deserves further investigation." (PMID 23158439, 2012). "One possibility to explain the tumor spectrum in Sdl mice and Mcm2 hypomorphic mice is that the integrity of the murine Notch1 locus is sensitive to replicative dysfunction in developing T cells and that replicative stress promotes the formation of type 2 deletions at the Notch1 locus." (PMID 23133403, 2012).
tumor (continued). "Furthermore, in order to determine whether Notch signaling was relevant to the tumor size, we analyzed the correlation of Notch1 and Jagged1 expression and tumor diameter in T1 stage ccRCC." (PMID 22506064, 2012). "In addition to their therapeutic potential, these antibodies may find utility as biomarker tools, for detection of Notch1 on the surface of tumor cells, and as probes of Notch1 function and signaling mechanisms." (PMID 20161710, 2010). "Notch1, which has no reported mutation in solid tumours, may likely use downstream effectors to execute its functions in tumour progression." (PMID 19953094, 2010). "Tumor development in the LADY mouse is associated with an increased rate of epithelial proliferation at both six and 16 weeks, increased expression of progenitor cell markers (Notch-1, Nestin) and decreased expression of terminal differentiation markers (Npdc-1 and probasin)." (PMID 17343742, 2007). "Notch1, Notch4 and ligands (DLL4, JAG1) are overexpressed in >70 % of HCC cases and related to advanced tumour stage and vascular invasion." (PMID 41476776, 2026). "Using tumor samples collected from the Lgr5-specific Ythdf1cki mouse model, qPCR analysis revealed that YTHDF1 knock-in increased the expression of NOTCH1 downstream targets, including MAML1, MAML2, HES1, and HEY1." (PMID 41423446, 2025). "In the present study, it was shown that APOL1 functioned as a tumor suppressor in THCA, whereas previous studies have identified APOL1 as an oncogene that promotes proliferation and inhibits apoptosis through the NOTCH1 signaling pathway." (PMID 41378287, 2025). "Atezolizumab increased tumor-infiltrating T cells, augmented by CRTC1 knockdown but blocked by Notch1 overexpression." (PMID 40977688, 2025). "We postulate that mesenchymal cells induced by NOTCH1 activation, though less abundant than typical epithelial cells within a given SCLC tumor, can promote an immune-inflamed tumor microenvironment through STING pathway activation." (PMID 40627448, 2025). "Different receptors have distinct roles; for example, NOTCH1 acts as a tumor suppressor, while NOTCH3 promotes tumor growth." (PMID 39928309, 2025). "Normally, circ_0000190 sponges miR‐130a‐3p, facilitating Notch1 pathway activation (Notch1, Hes1, VEGF), which supports tumor progression." (PMID 40796179, 2025). "To further explore how the 3D microenvironment in MCP-B hydrogels regulates tumor aggressiveness in HCC, we evaluated the expression of Notch1 and Notch2." (PMID 41149589, 2025). "Proteomic profiling further revealed its impact on multiple oncogenic and tumor-suppressive proteins, with notable upregulation of SERPINB2, KIT, and NOTCH1, alongside downregulation of COX2, DNMT1, MAPK1, AKT1, MKI67, EP300, and SMC1A." (PMID 41321870, 2025). "After binding to different Notch receptors (Notch1-4), DLL3 promotes malignant tumor transformation." (PMID 41375037, 2025). "Sustained inhibition of Notch1 activity and activation of Bcl-2, Bcl-XL and caspase-3 in breast cancer MCF-7 and MDA-MB-231 cells reduced and promoted tumor cell apoptosis." (PMID 40630953, 2025). "Nevertheless, larger-scale research using more sophisticated methodologies is recommended to clarify the mechanisms behind Notch1 and CD10 expression in tumor progression and resistance, and to validate their potential as targeted therapies in CRC." (PMID 40060224, 2025).
tumor (continued). "ShRNA-mediated knockdown of POFUT1 downregulates NOTCH1 signaling, leading to decreased cell proliferation, migration, and induced apoptosis in CRC cells in vitro, as well as suppression of CRC tumor growth and transplantation in vivo." (PMID 40286076, 2025). "Prior research has indicated that Notch1 possesses the capacity to regulate ABC transporters, proteins involved in cell death processes, thereby influencing the sensitivity of tumour cells to chemotherapy drugs." (PMID 40100070, 2025). "miR-34a acts as a tumor suppressor by targeting genes involved in EMT and metastasis, such as Notch1 and Fra-1, thereby reducing cell invasion and metastasis." (PMID 40958878, 2025). "All three tumor cell lines exhibited downregulation of MHC class I (H2-Kb) and expressing CD24, Notch1, and c-Myc, typical markers for T-ALLs." (PMID 40534857, 2025). "This subtype exhibited significant stem cell-like characteristics, marked by the high expression of key stemness genes such as EZH2, LGR5, NOTCH1, and ABCG2, which together formed a core regulatory network maintaining tumor stem cell properties." (PMID 40787449, 2025). "While our work focuses on the role of NOTCH1 in inducing tumor-intrinsic STING expression and activation, NOTCH1 has been shown to inhibit STING activation in CD4+ T cells via binding to the cyclic dinucleotide binding site." (PMID 40627448, 2025). "Tumours with low uPA and low PAI-1 concentrations (low uPA/PAI-1 status) showed a reduced NOTCH1 mRNA expression." (PMID 39153127, 2025). "POSTN (periostin) plays a pivotal role in tumour progression by interacting with ECM components and engaging WNT and NOTCH1 signalling pathways." (PMID 40038875, 2025). "They observed on a murine xenograft model of human BCa cells that NOTCH1 and MAPK signalling marked two distinct tumour cell subpopulations, and both contribute to tumour progression." (PMID 41008920, 2025). "To validate the expression of NOTCH1 in LUAD patients, we carried out an expression analysis and survival analysis of NOTCH1 across all four tumor stages with log2 (FC) values." (PMID 41451346, 2025). "Herein, we selected two representative Notch receptors (NOTCH1 and NOTCH2), NICD (NOTCH1 intracellular domain, also known as activated NOTCH1), and HES1 (downstream effector) as targets and conducted an immunohistochemical study on tumor samples." (PMID 40387567, 2025). "Consistent with the in vitro results, the combined inhibition of Notch1 and STAT3 induced a more potent delay in tumor growth and reduced tumor volume." (PMID 40019515, 2025). "Both NOTCH1 and NOTCH2 were expressed in AFX and PDS tumor cells, and the staining showed mostly a cytoplasmic pattern with or without a nuclear pattern." (PMID 40387567, 2025). "Conversely, MAML1 upregulation enhances Notch1 and Gli1 expression, driving accelerated TNBC tumor growth and faster multiorgan metastasis in vivo." (PMID 41272291, 2025). "NOTCH1 activation inhibits proliferation in BLCA cell lines, suggesting its role as a tumor suppressor." (PMID 40016843, 2025). "In human cell line models of FN-RMS, NOTCH1 regulates expression of SNAI1, increasing the number of proliferative, tumor propagating cells by repressing expression of MEF2C." (PMID 39902277, 2024). "Notch1 promotes the production of proinflammatory cytokines such as CCL2 and IL-1β, which improves the recruitment of tumor-promoting TAMs to the TME." (PMID 39735530, 2024).
tumor (continued). "We have calculated both Spearman and Pearson correlation coefficients for NOTCH1 and FGFR2 expression in relation to tumor progression." (PMID 39063983, 2024). "In vivo experiment chaetocin treatment significantly inhibit the growth of tumor, and reduce SUV39H1, Notch1, CD31 expression." (PMID 38650654, 2024). "The aim of our study was to characterize tumor and plasma metabolomes during T-ALL development using a NOTCH1-induced murine T-ALL model (ΔE-NOTCH1)." (PMID 38928249, 2024). "These correlation coefficients indicate a strong positive correlation between NOTCH1 and FGFR2 expression and their relationship with tumor progression, supporting our reported findings." (PMID 39063983, 2024). "Knockdown of NUMB, or overexpression of NICD (the active fragment NOTCH1) or SOX2, rescued the in vitro sphere-forming and in vivo tumor-forming abilities that were lost upon RAB4A knockdown." (PMID 39463384, 2024). "CNTN1 also serves as a functional ligand of Notch1 and promotes Notch1 activation by releasing the Notch intracellular domain (NCID), thereby promoting tumor progression." (PMID 38562021, 2024). "SPINK13 induces mitochondrial apoptosis and cell cycle arrest by triggering the Notch1/Hes1-PTEN/Akt signaling axis and reversing EMT, thereby inhibiting HCC cell nude mouse xenograft tumor subcutaneous growth." (PMID 39537605, 2024). "In OSCC, Notch1 up-regulates VEGF expression and promotes tumor angiogenesis (Cierpikowski, Lis-Nawara & Bar, 2023)." (PMID 38650654, 2024). "The observed opposite trends in NOTCH1 and FGFR2 expression can be attributed to their distinct roles in tumor biology." (PMID 39063983, 2024). "The Pearson correlation coefficients are as follows: NOTCH1 and FGFR2 expression, 0.988; NOTCH1 expression and tumor progression, 0.950; and FGFR2 expression and tumor progression, 0.948." (PMID 39063983, 2024). "The Spearman correlation coefficients are as follows: NOTCH1 and FGFR2 expression, 0.988; NOTCH1 expression and tumor progression, 0.953; and FGFR2 expression and tumor progression, 0.953." (PMID 39063983, 2024). "Oncogenes (e.g., NOTCH1 and ERBB2) tended to increase in centrality in tumor modules while tumor suppressors (e.g., BAP1, AKT1, and EP300) decreased in centrality." (PMID 38685127, 2024). "Both the sarco-sphere model as well as the corresponding tumor tissue harbored an in-frame EIF5A::USP6 fusion in chromosome 17, homozygous losses of CDKN2A/B and ATRK, a truncation in the NOTCH1 gene and a TCF3::SLC39A3 rearrangement." (PMID 37951844, 2024). "Circ 0000745 and notch receptor 1 (NOTCH1) were shown to be overexpressed in both T-ALL bone marrow and T-ALL cells, contributing to tumor development." (PMID 39439468, 2024). "While NOTCH1’s tumor-suppressive functions are more prominent in the initial, less aggressive stages of tumor formation, FGFR2’s oncogenic activities drive tumor progression and malignancy." (PMID 39063983, 2024). "The knockdown of FBP1 led to a significant increase in the formation of tumor spheres in PC9 cells, while the simultaneous knockdown of Notch1 reversed this trend." (PMID 38349431, 2024). "These distinct preventive combinations and second-line treatment option dependent on NOTCH1 and SOX2 expression in TNBC are able to induce tumor growth control and reduce metastatic burden." (PMID 39478150, 2024). "Considering the complex effects of the internal environment and tumor microenvironment, the GL261/KO1‐2 and GL261/NC cell lines were inoculated into mice subcutaneously to construct both NOTCH1 KO and NOTCH1 NC mice models of subcutaneous tumor, respectively." (PMID 39544152, 2024). "Recently, we reported that Crenigacestat, a gamma secretase inhibitor, targets the NOTCH1/DLL4/VEGFA/MMP13 axis, reducing iCCA progression in a patient-derived xenograft (PDX) model by blocking tumor neovascularization." (PMID 39415286, 2024). "And the knockout of Notch1 gene increased TMZ‐induced tumor proliferation inhibition and tumor cell apoptosis." (PMID 39544152, 2024).
tumor (continued). "More importantly, we found that the expression levels of Notch1 were positively correlated with BRD4 proteins in Western blot analysis and immunohistochemistry results of in vivo tumor samples." (PMID 39544152, 2024). "Th17 cells produce IL-17A, which facilitates cancer cell migration, invasion, and stemness through the STAT3/NF-κB/Notch1 signaling pathway, while also recruiting MDSC cells in the TNBC tumor microenvironment, further enhancing tumor progression." (PMID 39867914, 2024). "The activation of Notch pathway components, such as Notch receptors (Notch1-4) and their ligands (Jagged and Delta-like), orchestrates a cascade of downstream events that promote GSC maintenance and tumor progression." (PMID 39063221, 2024). "Particularly, inhibition of both Notch1 and Notch2 is responsible of GI toxicities observed in both animal models and patients, while Notch2 is required by CD8+ T cells for their anti-tumor cytotoxicity." (PMID 39491031, 2024). "Here, we sought to validate, in a xenograft mouse model, the essential role of NUMB, NOTCH1, and SOX2 in RAB4A-driven tumor formation." (PMID 39463384, 2024). "Immunohistochemical analyses revealed increased levels of TBC1D15, NUMB, NOTCH1, and TOM20 in the tumor tissues of NSG mice injected with CD133(+) TICs." (PMID 38409448, 2024). "Expression levels of Jagged1, MKP-1, MMP7, Notch1, SSBP2, and ZMIZ1 in tumor tissues of LV-ZMIZ1-RNAi CAL-27 mice were decreased compared to the control group (P < 0.05)." (PMID 38866828, 2024). "Subsequently, by inhibiting NOTCH1, the repression of CXCR4 resulted in a reduction in tumor growth." (PMID 37833915, 2023). "Intriguingly, tumors derived from the 501Mel (TRIM22low) cells were more sensitive to Notch1 inhibition by IMR-1, but tumors derived from MV14 (TRIM22high) cells exhibited resistance to Notch1 inhibition, as evidenced by tumor volumes and tumor weight." (PMID 37415153, 2023). "In agreement with this, it has been found that the inhibition of LUNAR1 in CRC decreases tumour growth and efficiently depletes IGF1 pathway activity, indicating a role for the LUNAR1/NOTCH1/IGF1R axis in cancer development." (PMID 37628760, 2023). "In summary, we observed an inverse relationship between NOTCH1 and NOTCH3 levels and cisplatin responsiveness, overall protective effects by CAFs, and a potential link between JAG2 expression with tumor cell survival." (PMID 38001580, 2023). "It has been discovered that epithelial NOTCH1 signaling is a prognosis-damaging subtype of CRC, and that it is capable of driving tumor cell metastasis through TGF β-dependent migration of neutrophils." (PMID 37600653, 2023). "Active Notch1 expression renders CD8 T-cells highly resistant to MDSCs and increases their anti-tumor activity." (PMID 37901240, 2023). "In the current study, 1 patient with NOTCH1-activating metastatic ACC and tumor BCL2 overexpression had additional tumor growth stabilization with the off-label addition of the BCL2 inhibitor Venetoclax to CB-103 after first progression." (PMID 37712875, 2023). "IHC staining of tumor sections revealed that the levels of ALDH1, CD44, CD133, SOX2, Notch1, EZH2 and CCND1 were downregulated in CDK5RAP2-knockdown tumors." (PMID 36774351, 2023). "KLF4, a vital regulator of the NOTCH pathway, promotes ineffective angiogenesis in tumors via the NOTCH pathway, leading to hypoxia and diminished tumor growth, and KLF4 also inhibits NOTCH-1 in combination with SP3 transcription." (PMID 36761967, 2023). "Results showed that the high value of regulatory potential between MFAP5 and some of its top predicted NOTCH1/WNT pathway target genes (CCND1, HES1, MYC, RBPJ, NOTCH1, CCN3, CTNNB1 and SOX17) in inferring signaling paths in tumour tissues." (PMID 36855786, 2023).